AQP9 (aquaporin 9)
Diseases named in the same sentence as AQP9 in open-access papers (continued):
Sharing a sentence is not in itself a finding about the gene and the disease.
Parkinson disease (5 papers, 2018 to 2023). A progressive degenerative disorder of the central nervous system characterized by loss of dopamine producing neurons in the substantia nigra and the presence of Lewy bodies in the substantia nigra and locus coeruleus. "Within the scope of neurodegenerative disorders, a potentially significant yet conjectural association has been proposed between Aquaporin-9 (AQP9) and Parkinson’s disease." (PMID 37762642, 2023). "Here we used an in vivo model of Parkinson’s disease where MPP+ was injected unilaterally into the striatum of Aqp9 deficient and WT mice." (PMID 29566083, 2018). "Renewed interest in brain AQP9 is now kindled by the recent discovery that Aqp9 deletion protects against MPP+-induced cell death in a mouse model of Parkinson ́s disease." (PMID 37189335, 2023). "Furthermore, AQP9, selectively expressed in catecholaminergic neurons, had been shown to infiltrate parkinsonogenic toxins, which is important in the pathophysiology of Parkinson's disease." (PMID 34540996, 2021). "Thus, both AQP4 and AQP9 are relevant in the context of Parkinson’s disease." (PMID 33167342, 2020).
renal cell carcinoma (5 papers, 2021 to 2026). "Moreover, recent findings showed AQP9 as a target for both miR-532-5p and miR-532-3p in renal cell carcinoma (RCC) cells, being its aberrant expression intimately associated with poor prognosis of RCC patients." (PMID 35187089, 2022). "High expression levels of AQP9 in renal cell carcinoma individual had the trend of bad prognosis." (PMID 33643388, 2021).
Stroke (5 papers, 2020 to 2024). Sudden impairment of blood flow to a part of the brain due to occlusion or rupture of an artery to the brain. "We aimed to investigate the associations between genetic variants in AQP7 and AQP9 and the risk of stroke among patients with hypertension, as well as to explore gene-gene and gene-environment interactions." (PMID 32309443, 2020). "This is the first study in China, which investigated the association between genetic variants in AQP7 and AQP9 and the risk of stroke among hypertensive patients." (PMID 32309443, 2020). "The analysis, which included 14,746 African Americans, found a novel SNP associated with total stroke in the 15q21.3 locus which is located near the Aquaporin 9 gene (AQP9), the aldehyde dehydrogenase 1 family, member A2 (ALDH1A2) and hepatic lipase (LIPC) genes." (PMID 34828431, 2021). "Therefore, this study is aimed at investigating the associations between AQP7 and AQP9 genetic variants and the risk of stroke among patients with hypertension." (PMID 32309443, 2020). "However, limited epidemiological studies explore the associations between AQP7 and AQP9 and the risk of stroke among patients with hypertension in China." (PMID 32309443, 2020). "Dysregulations of AQP7 and AQP9 were found to be related to lipid metabolism abnormality, which had been proven to be one of the mechanisms of stroke." (PMID 32309443, 2020). "Dysregulation of AQP7 and AQP9 may result in lipid metabolism abnormality, which is one of the important mechanisms of stroke." (PMID 32309443, 2020). "However, epidemiological studies on the associations between AQP7 and AQP9 and the risk of stroke among patients with hypertension are still largely lacking." (PMID 32309443, 2020). "In gerbil models of ischemic stroke, AQP9 is expressed in hippocampal pyramidal neurons in regions CA1, CA2, and CA3 as early as 6 h post-stroke onset, a pattern distinct from other stroke models." (PMID 37762642, 2023). "Consistent with our findings, other authors reported an enrichment in molecular processes related to cardiomyocyte death, implicating PTEN and inflammation, including AQP9, PTEN, or SMARCA4 (recognized for its involvement in heart fibrosis), in the blood of CE stroke patients." (PMID 38673963, 2024). "Lastly, we predicted 53 potential drugs that may exert neuroprotective effects in early stroke by targeting 5 genes (STAT3, MMP9, AQP9, SELL, FPR1)." (PMID 37180174, 2023).
acute myeloid leukemia (4 papers, 2015 to 2022). Acute myeloid leukemia (AML) is a group of neoplasms arising from precursor cells committed to the myeloid cell-line differentiation. "The expression level of AQP9 was related to sensitivity to As2O3 in acute promyelocytic leukemia, and azacytidine upregulated AQP9 to make acute myeloid leukemia cells more sensitive to As2O3." (PMID 35972604, 2022). "AQP9 expressed in acute myeloid leukemia was permeable to As2O3, and upregulated AQP9 enhanced cytotoxicity in acute myeloid leukemia cell lines, expanding the therapeutic spectrum of As2O3." (PMID 36254092, 2022). "Improving the expression of AQP9 is the key point to overcoming ATO resistance in acute myeloid leukemia." (PMID 35590355, 2022). "Of the different subtypes of acute myeloid leukemia (AML), APL cells express the highest concentration of AQP9, which might in part explain their exquisite sensitivity to As2O3." (PMID 25953102, 2015).
brain edema (4 papers, 2014 to 2023). Increased intracellular or extracellular fluid in brain tissue. "The role of other aquaporin family members, such as Aquaporin-9, in the resolution of cerebral edema warrants exploration." (PMID 37762642, 2023). "In contrast to AQP9, AQP4 appears to collaborate with other astrocytic proteins such as Connexin-43 (Cx43) and the potassium channel Kir4.1 in managing cerebral edema." (PMID 37762642, 2023).
Cerebral ischemia (4 papers, 2014 to 2023). Restriction of arterial blood supply to the brain associated with insufficient oxygenation to support the metabolic requirements of the tissue. "Matrix metalloproteinase 2 (MMP2), aquaporin (AQP) 4, and AQP9 are linked to permeabilization of the blood-brain barrier (BBB) in cerebral ischemia/reperfusion injury (CIRI)." (PMID 24828425, 2014). "In brain ischemia models, previous studies have shown that AQP9 could regulate post-ischemic edema." (PMID 29540536, 2018). "Moreover, another three potential drugs, phloretin, cucurbitacin B, and bimosiamose, which are the inhibitors of AQP9, STAT3, and SELL, respectively, have been reported to improve neurologic deficits after rat cerebral ischemia by reducing oxidative stress." (PMID 37180174, 2023).
cholestasis (4 papers, 2013 to 2025). Impairment of the bile flow caused by obstruction within the liver, or outside the liver in the bile duct system. "Misrouted hepatocyte AQP9 associated with decreased water and glycerol membrane permeability has also been reported in a rat model of extra-hepatic cholestasis." (PMID 24205128, 2013). "Additionally, AQP8 and AQP9 expression is reduced in the livers of rats with ligated bile ducts, whereas increased AQP1 expression alleviates cholestasis." (PMID 40115259, 2025). "The altered expression of liver AQP9 induced by the cholestasis did not depend on insulin, a hormone downregulating AQP9 at the transcriptional level, since insulinemia in BDL rats was unchanged." (PMID 35883453, 2022).
colon cancer (4 papers, 2015 to 2025). "Besides, AQP5 and AQP9 were associated with the resistance of colon cancer to drugs." (PMID 25886458, 2015). "Thus, AQP5-p38 MAPK pathway and AQP9 would be a new therapeutic target to improve drug resistance of colon cancer." (PMID 25886458, 2015). "Conversely, colon cancer patients non-responsive to adjuvant chemotherapy were more likely to have low AQP9 expression." (PMID 32679804, 2020).
oligohydramnios (4 papers, 2016 to 2021). A lower than normal quantity of amniotic fluid in the amniotic sac as compared to normal values. "In patients with oligohydramnios, AQP9 expression was positively associated with AQP1 expression in both placental trophoblasts (P < 0.05, r = 0.640) and foetal membranes (amnion epithelial cells and chorion cytotrophoblasts) (P < 0.05, r = 0.634)." (PMID 32542408, 2020). "Moreover, it was shown that Aquaporin-8 and Aquaporin-9 levels were significantly decreased in amnion and increased in placenta in fetuses suffering from oligohydramnios, further supporting the effect of aquaporins in amniotic fluid levels." (PMID 33902516, 2021). "Furthermore, AQP9 expression was associated with AQP1 level in the placenta and foetal membranes in oligohydramnios." (PMID 32542408, 2020). "The expression of aquaporin 8 and aquaporin 9 in amniotic membrane of oligohydramnios group is significantly lower than that of normal amniotic fluid group, however, it has not been shown which lncRNAs regulate the expression of aquaporin 8 and aquaporin 9 in oligohydramnios group." (PMID 32948205, 2020). "However, in oligohydramnios patients, AQP9 expression in the placenta and foetal membranes was positively correlated with AQP1 expression in both placental trophoblasts and amnion epithelial cells." (PMID 32542408, 2020). "Compared with patients with a normal AFV, patients with oligohydramnios exhibited dramatically decreased AQP1 and AQP9 expression in the foetal membrane and placental trophoblasts (P < 0.05)." (PMID 32542408, 2020). "In our previous study, AQP1 and AQP9 expression in the amnion was decreased in pregnancies with isolated oligohydramnios, so pregnancies with oligohydramnios and a normal AF volume were selected to establish the correlation between AQP1 and AQP9 protein expression." (PMID 32542408, 2020).
rheumatoid arthritis (4 papers, 2014 to 2023). A chronic, systemic autoimmune disorder characterized by inflammation in the synovial membranes and articular surfaces. "Furthermore, a microarray study on peripheral blood mononuclear cells of patients with irritable bowel syndrome, psoriasis, and rheumatoid arthritis, identified AQP9 as a novel marker of chronic inflammation underlying these diseases." (PMID 27518164, 2016). "Apart from its contribution to neoplasm pathogenesis, AQP9 has also been implicated in the process of inflammation; a previous study indicated that a strong increase in AQP9 transcripts was observed in synovial tissues from patients with osteoarthritis and rheumatoid arthritis." (PMID 24959239, 2014).
acute promyelocytic leukemia (3 papers, 2022 to 2024). An aggressive form of acute myeloid leukemia (AML), characterized by arrest of leukocyte differentiation at the promyelocyte stage, due to a specific chromosomal translocation t(15;17) in myeloid cells. "Cell proliferation was analyzed in the acute promyelocytic leukemia (APL) cell line NB4 which showed expression of all three aquaglyceroporins AQP3, AQP7, and AQP9." (PMID 38319972, 2024). "In human acute promyelocytic leukemia (APL) cell lines, NB4 and HT93A, and primary APL cells, the expression level of AQP9, rather than other biomarkers, correlated with sensitivity to arsenic trioxide in both APL cell lines and primary cells." (PMID 35883453, 2022).
atherosclerosis (3 papers, 2012 to 2022). A disease characterized by the build-up of fatty material and calcium deposition in the arterial wall resulting in partial or complete occlusion of the arterial lumen. "Since genetic variation and gene expression of SERPINA1 and AQP9 were associated with lipoprotein levels, lipid transporters central to atherosclerosis, we investigated the relationship between these genes and atherosclerosis." (PMID 22916037, 2012). "Finally, we show that the genes are associated with atherosclerosis using mouse atherosclerotic lesion size (AQP9) as well as tissue from healthy human arteries and atherosclerotic plaques (AQP9 and SERPINA1)." (PMID 22916037, 2012). "Further functional work will need to be performed to elucidate the biological role of SERPINA1 and AQP9 in atherosclerosis." (PMID 22916037, 2012). "We detected 7 novel loci and investigated the gene expression of our top loci, SERPINA1 and AQP9, in multiple human tissues as well as their potential role in atherosclerosis." (PMID 22916037, 2012). "We also speculate that the roles of SERPINA1 and AQP9 in atherosclerosis are tissue-specific where AQP9 displays an effect in both liver and arterial tissue and SERPINA1 only in the latter." (PMID 22916037, 2012). "The TVS results suggest that both AQP9 and SERPINA1 are candidate genes for atherosclerosis." (PMID 22916037, 2012).
endometriosis (3 papers, 2019 to 2020). The growth of functional endometrial tissue in anatomic sites outside the uterine body. "They found that the expression for AQP2 and AQP8 was significantly higher than the other isoforms; moreover, the expression of AQP9 was decreased in the eutopic endometrium of patients with endometriosis when compared with the control group." (PMID 32046116, 2020). "Also, this work stated that the endometrial expression of AQP9 was significantly decreased in the eutopic endometrium of patients with endometriosis as compared with that of healthy women." (PMID 33321760, 2020). "Taken together, these findings may suggest a role of AQP9 in the pathogenesis of endometriosis." (PMID 32046116, 2020).
endotoxemia (3 papers, 2021 to 2025). "In an animal model of lipopolysaccharide (LPS)-induced endotoxemia, Aqp9-KO mice showed increased survival compared with wild-type mice." (PMID 38279209, 2024). "A working model is proposed to explain how AQP9 intervenes in the early acute phase of the inflammatory reactions that are triggered by LPS in endotoxemia." (PMID 33670755, 2021). "In general, many additional pro-inflammatory mediators controlled by NF-κB p65 are known (e.g., TNF-α, IL-1β, IL-6 and MCP-1) and their contribution to the observed effects of Aqp9 deletion on the survival to endotoxemia can be anticipated." (PMID 33670755, 2021). "The modulation of AQP9 expression/function may reveal to be useful in developing novel endotoxemia therapeutics." (PMID 33670755, 2021).
Infertility (3 papers, 2018 to 2025). "Our results show that exposure of mSCs to high levels of E2 causes a decrease in Aqp9 expression, which leads to decreased glycerol permeability and can lead to dysregulation of the concentration of glycerol in the testis, causing fertility problems or even infertility." (PMID 30274223, 2018). "AQP9 is also expressed in other tissues, and their altered expression is described in several human diseases, such as liver injury, inflammation, cancer, infertility, and immune disorders." (PMID 35883453, 2022). "Specifically, the expression of aquaporin-9, a water channel protein essential for follicular fluid accumulation during antrum formation in mice, is significantly reduced in GCs from women with PCOS compared to infertile women with tubal factor infertility." (PMID 40723795, 2025).
injury (3 papers, 2016 to 2025). Damage inflicted on the body as the direct or indirect result of an external force, with or without disruption of structural continuity. "Earlier research has established that AQP1, AQP4, AQP2 and AQP9 are associated with spinal cord injury- or nerve injury-induced nerve pain in rats." (PMID 35324416, 2022). "The expression of AQP9 in neurons also indicated that AQP9 plays a role in energy balancing after traumatic brain injury." (PMID 27218255, 2016).
ischemia (3 papers, 2018 to 2025). A hypoperfusion of the BLOOD through an organ or tissue caused by a PATHOLOGIC CONSTRICTION or obstruction of its BLOOD VESSELS, or an absence of BLOOD CIRCULATION. "AQP9 supports energy metabolism in neurons and astrocytes affected by ischemia and vasospasm." (PMID 40564125, 2025). "In the cardiovascular system AQP1, AQP4, AQP7, and AQP9 are expressed in endothelial cells, vascular smooth muscle cells, and cardiac tissue which all play a vital role in the development and progression of pathologies such congestive heart failure, ischemia, hypertension, and angiogenesis." (PMID 30555637, 2018).
myeloma (3 papers, 2021 to 2022). "In contrast, p38 inhibition can suppress the expression of water channel protein aquaporin 4 (AQP4) and aquaporin 9 (AQP9) in cultured rat astrocytes; thus, it can enhance arsenic trioxide (As2O3)-induced cytotoxicity in myeloma cells." (PMID 35967171, 2022).
osteoarthritis (3 papers, 2014 to 2022). A noninflammatory degenerative joint disease occurring chiefly in older persons, characterized by degeneration of the articular cartilage, hypertrophy of bone at the margins and changes in the synovial membrane. "The downregulation of AQP9 was observed in the cartilage cells, which would cause the decomposition-related genes of stimulating the IL-1β that is down-expressed in osteoarthritis." (PMID 35531067, 2022).
periodontitis (3 papers, 2022 to 2026). An acute or chronic inflammatory process that affects the tissues that surround and support the teeth. "AQP9 mRNA expression is associated with the prevalence of caries or periodontitis and could represent a novel biomarker." (PMID 41688535, 2026). "AQP9 mRNA expression was increased in patients with severe caries compared to milder forms (p = 0.0120), and increased AQP9 expression was also detected in patients with periodontitis compared to unaffected individuals (p = 0.0364)." (PMID 41688535, 2026). "In this study we examined if AQP9 could serve as a biomarker for caries and periodontitis." (PMID 41688535, 2026). "Meanwhile, four genes, including FPR1, AQP9, BCL2A1, and VNN2 showed significantly higher expression in periodontitis patients and were strongly correlated with neutrophil infiltration, emerging as central to diagnosis and understanding of periodontitis." (PMID 41009952, 2025). "However, the functional roles of AQP9 and BCL2A1 in periodontitis remain poorly understood, and further studies are needed to clarify their specific contributions to disease progression." (PMID 41009952, 2025). "In periodontitis, MANSC1 was negatively correlated and the other four hub crosstalk genes (FMNL1, PLAUR, RNASE6, and TCIRG1) were positively correlated with five hub IRRGs, namely, AQP9, C5AR1, CD14, CSF3R, and PLAUR." (PMID 36545026, 2022).
polycystic ovary syndrome (3 papers, 2013 to 2024). A disorder that manifests as multiple cysts on the ovaries. "In females, AQP9 is downregulated in polycystic ovary syndrome (PCOS) and is associated with hyperandrogenism." (PMID 38674035, 2024). "For example, in polycystic ovary syndrome (PCOS), decreased AQP9 expression in the granulosa cells was associated with hyperandrogenism, influencing the maturation of PCOS follicles." (PMID 35883453, 2022).
Polyhydramnios (3 papers, 2016 to 2020). The presence of excess amniotic fluid in the uterus during pregnancy. "In polyhydramnios cases, the expression of AQP8 in the amnion and that of AQP9 in the amnion and the chorion were significantly increased in the idiopathic polyhydramnios group; however, their expression in the placenta was significantly decreased." (PMID 29194396, 2017). "Hence, upregulation of AQP8 in the foetal membranes after AQP1 depletion may lead to polyhydramnios through a compensatory mechanism, while the expression of AQP9 in the placenta and foetal membranes is decreased after AQP1 depletion." (PMID 32542408, 2020).